TNF (tumor necrosis factor)
Diseases named in the same sentence as TNF in open-access papers (continued):
Sharing a sentence is not in itself a finding about the gene and the disease.
Stroke (continued). "Various proinflammatory mediators, such as TNF-α and COX-2, are upregulated after stroke." (PMID 24348730, 2013). "CD4+ TH1 cells may progress stroke through releasing proinflammatory cytokines, including IL-2, IL-12, IFN-γ, and TNF-α, whereas CD4+ TH2 cells may play a protective role through releasing anti-inflammatory cytokines such as IL-4, IL-5, IL-10, and IL-13." (PMID 23431245, 2013). "Our findings show that the polymorphisms of TNF-α promoter may function as an important risk factor for ischemic stroke and our meta-analysis data confirmed that patients with acute ischemic stroke compared to controls without stroke have significantly higher median serum levels of TNF-α." (PMID 23050663, 2012). "Indeed, several traditionally pro-inflammatory stimuli, including lipopolysaccharide (LPS), tumor necrosis factor-α (TNF-α), and even brief ischemia, upregulate signaling pathways that induce stroke tolerance." (PMID 22340958, 2012). "Furthermore, unaltered levels of TNF-α and INF-γ in the ischemic hemisphere demonstrate a distinct attenuation of MCP-1 expression after stroke." (PMID 21625615, 2011). "The induction of IL-1α, IL-1β, TNFα MCP-1, RANTES, G-CSF, KC mRNA and increased MCP-1, RANTES, G-CSF protein levels in the brain after systemic LPS challenge are likely to result in a primed proinflammatory response by the time experimental stroke is induced." (PMID 22114895, 2011). "Reducing the brain temperature affected the stroke induced increase in interleukin-1β and tumor necrosis factor α in the striatum, 8 hours after its induction, but not at later time points." (PMID 21627837, 2011). "The TNF protein level in aged mice brains following stroke showed an elevated expression but was not significantly affected." (PMID 22028848, 2011). "MBL-low patients showed a cytokine profile after stroke characterized by a greater increase of IL-10, a lower rise of IL-6, and no significant changes of TNF-α compared to patients with MBL-sufficient genotypes." (PMID 20140243, 2010). "While there is no consensus on the role of TNF-α after stroke, there is also as of yet no consensus on the effect of hypothermia on TNF-α." (PMID 21040547, 2010). "Among stroke patients, IL-6 and IL-1 receptor antagonist, but not TNFα, measured at baseline were independent predictors of worsening in the first 24 hours after stroke." (PMID 17042946, 2006). "The evidence indicates distinct prognostic patterns: biomarkers of inflammation (e.g., TNF-α, IL-6, IL-1β) and neuronal or glial damage (e.g., S100B, GFAP, NSE, NfL) tend to correlate with less favorable outcomes, especially when measured in the acute phase of a stroke." (PMID 41598337, 2026). "In addition, it was also able to significantly inhibit PAF, IL-6, TNF-α, ICAM-1, and VCAM-1, which significantly improved cognitive function, attenuated anxiety-like behaviors, and promoted post-stroke brain function and motor recovery in stroke rats." (PMID 40837062, 2025). "A larger adiposity could therefore neutralize the negative effects of local TNF-α synthesis after stroke." (PMID 38732147, 2024). "Through flow cytometric analysis and immunostaining, we demonstrated that within 14 days postischemic stroke, the proinflammatory characteristics of microglia and macrophages gradually accumulated, as evidenced by the progressively elevated expression of IFN‐γ and TNF‐α." (PMID 39698742, 2024). "Also, patients with a history of myocardial infarction or stroke exhibited a higher serum TNF concentration than patients without those complications in their medical history." (PMID 38396488, 2024). "Thus, MLC601 and MLC901 reduce infarct size and ischemia-induced neurological deficits, attenuate cerebral ischemia-induced pro-inflammatory cellular infiltration, and attenuate stroke-induced increased expression of pro -inflammatory mediators (IL11, IL1β, IL6 and TNFα) in the brain." (PMID 36975881, 2023).
Stroke (continued). "The meta-analysis of studies on biomarker changes after stroke rehabilitation revealed that rehabilitation can significantly increase the concentration of serum BDNF and NE, and peripheral blood SOD, ALB and HB, and CAT, and decrease the biomarkers of serum ET, glutamate, and TNF-α." (PMID 37731856, 2023). "TNF is largely thought of as a negative factor, but can also have beneficial effects in stroke." (PMID 38240014, 2023). "Since 88.2% of patients had mRS score of ≤ 3 on day 90 after stroke, the correlation between TNF-α levels and disease outcome could not be ascertained." (PMID 36056287, 2023). "Moreover, the relationship between the TNF-α levels measured during onset and the NIHSS scale on admission (R = 0.4, p = 0.02) as well as mRS values assessed on admission (R = 0.33, p = 0.01) and in the 3rd month since the stroke (R = 0.47, p < 0.01)." (PMID 36142524, 2022). "In a transient MCAO model, the use of minocycline promoted microglia M2 polarization significantly reduced TNF and IL-1β levels and increased TGF-β, IL-10 and chitinase-like proteins (YM1) levels, thereby reducing cerebral infarct size, promoting vascular remodeling, and improving stroke prognosis." (PMID 35356292, 2022). "The plasma level of IL-6, but not TNFα, sIL-6R, or IL-1ra, was higher in patients who developed depressive symptoms at 3 months after IS; plasma IL-6 predicted the severity of depressive symptoms at 3 months after stroke." (PMID 36547090, 2022). "Importantly, a significant reduction in the volume of the infarcted area occurred in hybrid mice expressing nonfunctional Fas ligand and in TNF knockout mice 24 h after stroke." (PMID 36824441, 2022). "Current research on TNF in PSN has focused on drug development, focusing on effectively improving the development of neuroinflammation by inhibiting or promoting the expression of a certain TNF, which is related to the articles covered in cluster #8 (Stroke Recovery)." (PMID 36389810, 2022). "Finally, some potential indicators, such as the size of the stroke area, and other biomarkers of inflammation(i.e.,IL-6, TNF-α) were not included in the study." (PMID 36206280, 2022). "The spleen regulates the peripheral immune response after ischemic stroke by increasing circulating lymphocytes, proinflammatory cytokines, and chemokines (such as TNF-α, MCP-1, IFN-γ, IL-6, and IL-2) and may also aggravate the inflammatory response in the acute stage of stroke." (PMID 36474712, 2022). "Considering the continuous increase in stroke morbidity/mortality and the lack of non-invasive biomarkers of the disease, our study aimed to evaluate TNF-α, IL-6, and IL-10 levels in the non-stimulated (NWS) and stimulated (SWS) whole saliva of stroke patients." (PMID 34433866, 2021). "Furthermore, mice receiving young microbiome possessed much higher levels of IL-4 and granulocyte-colony stimulating factor (G-CSF), while the elevation of levels of IL-6, tumor necrosis factor alpha (TNF-α), Eotaxin, and CCL5 were shown in the mice with aged microbiota after stroke." (PMID 33439913, 2021). "Moreover, unlike the increase in TNF-α secretion from Mo upon exposure to highest dose of atorvastatin alone, combination of atorvastatin and aspirin did not affect TNF-α secretion from stroke monocytes." (PMID 33959001, 2021). "No strokes were observed in 2027 patient months since anti-TNF treatment was initiated, P < 0.0001." (PMID 35095905, 2021). "Moreover, MEDS-23 significantly decreased prostaglandin E2 levels in the hypothalamus and hippocampus of post-stroke rats, but did not prominently alter the levels of interleukin-6 and tumor necrosis factor-α." (PMID 35053779, 2021). "Furthermore, based on KEGG analysis, the therapeutic effects of luteolin on stroke may have through various pathways like the TNF signaling pathway, which overlapped with the results of KEGG analysis of stroke targets." (PMID 34898370, 2021).
Stroke (continued). "Of interest, TNF-α contributes to the dysfunctional activation of endothelial cells in the blood–brain barrier (BBB), increasing their production of cytokines, ROS, and adhesion molecules, while reducing their barrier function which is a known determinant of stroke outcome." (PMID 33770265, 2021). "In addition, to explain the relationship between stroke-related inflammatory processes and PSF, various interleukins and inflammatory cytokines, such as tumor necrosis factor-α (TNF-α), which are difficult to use in daily clinical settings, were used as indicators." (PMID 34828631, 2021). "TNF-α significantly down-regulates the VE-cadherin, ZO-1, and claudin-5 expression by shifting them to the cytoplasmic side from membrane and leads to increase EVs trafficking through BBB in vitro, suggesting under stroke-like condition EVs can cross BBB throughout the paracellular route." (PMID 34294165, 2021). "Pre-clinical studies show that selected serum biomarkers including C-reactive protein (CRP), interleukin-6 (IL-6), tumor necrosis factor-alpha (TNFα), matrix metallopeptidases (MMP), and vascular endothelial growth factors (VEGFs) may play a role in BBBP post-stroke." (PMID 34744972, 2021). "In diabetic patients with lacunar stroke, activation levels of TNFα and IL-1β in the acute phase (24–72 h) and subacute phase (7–10 days) of stroke were lower, compared to non-diabetic patients, which could be associated with their better outcome." (PMID 31701356, 2020). "Furthermore, we confirmed that the proinflammatory cytokines IFN-γ, TNF-α, and IL-6 were elevated in plasma even 12 months after MCAO compared with those in the sham-12 m group, indicating that chronic systemic inflammation persists after stroke onset." (PMID 31316450, 2019). "Although no significant changes in pro-inflammatory cytokine (IL-1β, IL-6, TNF-α) and chemokine (MCP-1, MIP-2α) gene expression were observed at 6 h, 24 h and 72 h after the 50 min ischemic occlusion, IL-1β, IL-6 and MIP-2α expression tended to increase 6 h after stroke." (PMID 30842652, 2019). "Experiments performed by the Lee group showed decreases in the expression of pro‐inflammatory cytokines TNF‐α, IL‐6, IL‐1β, cell adhesion molecules ICAM‐1 and VCAM‐1, and chemokines MCP‐1 and MIP‐1α after intraparenchymal transplantation of fetal‐ and iPSC‐NSCs in a rodent stroke model." (PMID 30747485, 2019). "TNF-α can activate microglia and astrocytes and have a modulatory effect on BBB permeability, and may also have several positive and negative effects on synaptic transmission and synaptic plasticity during stroke rehabilitation." (PMID 31031649, 2019). "In addition, the phagocytic behavior of alveolar macrophages obtained from naïve animals was reduced, whereas gene expression of TNF-α and IL-6 in these cells was increased, after exposure to serum from Stroke (but not Sham) rats." (PMID 30290827, 2018). "Furthermore, anti TNF-α therapy ameliorates functional outcomes after stroke by altering the peripheral immune response but without any impact on infarct volume." (PMID 30057552, 2018). "Indeed IL-6 has been seen to have neurotrophic and anti-inflammatory effects; in the stroke study IL-6 and TNF-α were inversely correlated, suggesting IL-6 might counterbalance the potential detrimental effects of TNF-α." (PMID 28253907, 2017). "Therefore we can conclude that worsening of the stroke pathology in LysMcreTNFfl/fl mice is dependent on the lack of microglial-derived TNF." (PMID 27384243, 2016). "In C57BL/6 mice at 7 weeks post-stroke there were increased levels of G-CSF, GM-CSF, IFNγ, IL-1α, IL-5, IL-6, IL-12 (p40), IL-12 (p70), IP-10, KC, MCP-1, MIP-1α, MIP-1β, MIP-2A, RANTES, and TNFα within the infarct compared to the equivalent area of cortex from sham mice." (PMID 27600707, 2016).
Stroke (continued). "The production of IFN-γ by TH1 cells, proliferation of T cells and cytokine responses, TNF-α production by macrophages and cytokine production by monocytes are all inhibited by IL-10 to further emphasize its role in the immune shift toward a TH2 response and immune suppression after stroke." (PMID 26742037, 2016). "Indeed, TNFα, IL-1α, IL-1β, CCL2, CCL3 and CX3CR1 transcript expression differed in the ischemic cerebral tissue of TREM2-KO mice compared to littermate controls at day 7 after stroke." (PMID 23301011, 2013). "In an experimental stroke model, intranasal BDNF was shown to modulate local inflammation and protect against cerebral ischemia by upregulating anti-inflammatory cytokine IL-10, down-regulating the pro-inflammatory cytokine TNF-α, and in turn increasing the DNA-binding activity of NFKB." (PMID 23912236, 2013). "Up-regulated serum and brain pro-inflammatory cytokines elicited by TBI or stroke were attenuated by treatment with rhEPO, although EPO administration enhanced BDNF up-regulation elicited by cerebral ischemia, but did not prevent inflammatory gene up-regulation (e.g., IL-1β, IL-6, TNF-α)." (PMID 23675319, 2013). "Among these proinflammatory mediators, tumor necrosis factor (TNF)-α is an important effector of immune response in the brain and is involved in the pathogenesis of several acute and chronic neurodegenerative disorders, such as Parkinson's disease, Multiple Sclerosis, and stroke." (PMID 23236394, 2012). "The results suggest that inhibition of TNF signaling pathways by inhibition of the intracellular MAPK ERK1/2 pathway may constitute interesting targets, whereby inflammatory processes elicited following stroke may be prevented or attenuated." (PMID 21871121, 2011). "Observation of similar TNF-α levels in patients with and without risk factors, other than those with DM on day 7 and with TIA at baseline, refuted this hypothesis and proposed ischemic injury as the main inducer of TNF-α in stroke patients." (PMID 36056287, 2023). "The present bibliometric analysis shows a continuous trend of increasing literature related to TNF in PSN, and shows that TNF plays an important role in PSN involves multiple immune mechanisms and may contribute as a potential target for neuroprotective therapeutics after stroke." (PMID 36389810, 2022). "Although the change in IL-10 with clenbuterol at 4 h after stroke is not significant, this data is consistent with previous reports that stimulation of β2-adrenergic receptors with clenbuterol or norepinephrine induces IL-10 expression and suppresses TNFα expression." (PMID 31138227, 2019). "Interestingly the serum levels of IL-1β and TNF-α exhibited the same pattern as that of MHC II on microglia, and the infiltration of peripheral leukocytes also showed the similar pattern, especially the pattern of lymphocytes that exhibited a close correlation to the stroke outcomes." (PMID 27405096, 2016). "The CSF levels of IL-1 β and TNF-α were found to be increased, but not significantly, in severe stroke patients at the time point examined in this study but might become significant at later stages of stroke." (PMID 21450100, 2011). "The model explicitly incorporates nonlinear feedback (IL-10 suppression of TNF-α/IL-6), cross-activation (NF-κB-mediated TNF-α/IL-6 synergy), and empirical parameterization from clinical stroke data." (PMID 41557608, 2026). "Silymarin raised cortical TNFα, IL4, IL10, IGF1, BDNF, and CX3CL1 levels in the HFD group with stroke, while the striatum did not present relevant differences." (PMID 39624169, 2024). "There was no statistical significance between stroke characteristics and telomere length, NR3C1, TNF-α, BDNF, MTNR1A, or MTNR1B expression." (PMID 38802847, 2024). "We used the measured values of iFABP, IL-6, and TNF-α in both PSD and non-PSD stroke patients to construct an OPLS model and evaluate the relationship between the expression levels of these biomarkers and group classification." (PMID 38084247, 2023).
Stroke (continued). "Unlike TNF-α and SDF-1, no significant variation was observed in the levels of VEGF and PDGF-BB between IS patients and HVs until day 90 post-stroke." (PMID 36056287, 2023). "We confirmed that brain IL-6, IL-1β, TNF-α, CCR2, and MCP-1 expression levels were not significantly different between ND/veh and DD/STZ mice prior to stroke (data not shown)." (PMID 35784349, 2022). "In animals of both sexes, post-stroke WBV significantly reduced circulating pro-inflammatory cytokines IL-6, IFN-gamma, and TNF alpha as compared to the respective No-WBV group." (PMID 36062148, 2022). "Losartan did not change secretions of any measured cytokines from stroke-derived Mo but reduced MCP-1 and TNF-α from healthy control Mo." (PMID 32802081, 2020). "The multiple linear regression analysis was used to analyze age, gender, BMI, mRS, CAT, SOD, hydrogen peroxide, MDA, TNF-α, and IL-6 for factor independently correlated with HGS in non-paretic and paretic limbs of stroke patients." (PMID 33126675, 2020). "In our study, we reported higher serum levels of IL-6 and TNF-α and higher percentage of peripheral CD4+ cells and CD4+CD28 null in subjects with acute ischemic stroke in comparison with subjects without stroke." (PMID 30995924, 2019). "Whole lung gene expression of IL-1β, TNF-α and MCP-1 was not altered at any of the time-points post stroke, but there was an increase in IL-6 and MIP-2α at the 6 h time-point." (PMID 30842652, 2019). "In subjects with CEI subtype and metabolic syndrome, PWV was more significantly and positively related to vWF but not with TNF-α, CRP, IL-6, IL-1β and PAI-1 compared to subjects without metabolic syndrome and the same subtype of stroke." (PMID 24571954, 2014). "In subjects with stroke classified as LAAS and metabolic syndrome, PWV was more significantly and positively related to CRP, IL-1β, IL-6, TNF-α, vWF and PAI-1 compared to subjects without metabolic syndrome and the same subtype of stroke." (PMID 24571954, 2014). "Prior to stroke, the basal MCP-1 gene expression in the diabetic peritoneal cells was highly elevated while IL-1β and TNFα were not different between normal and diabetic peritoneal cells (data not shown)." (PMID 24886035, 2014). "While computational models have explored isolated aspects of post-stroke inflammation, such as TNF-α-mediated microglial activation or IL-6’s dual neurotoxic/neuroprotective roles, no study has yet integrated TNF-α, IL-6, and IL-10 into a unified mathematical model." (PMID 41557608, 2026). "In a stroke model, VEGF-C pretreatment suppressed microglial activation and pro-inflammatory signaling (including TNF-α/NF-κB and interferon pathways), while promoting non-inflammatory microglial states and neurotrophic signaling, indicating a dual anti-inflammatory and neuroprotective role." (PMID 41099766, 2025). "Regarding TNF-α and IL1-β, there were no level differences related to the stroke time." (PMID 36835156, 2023). "Tumor necrosis factor-α (TNF-α) is another marker of CVD in older patients, but not of stroke." (PMID 36555671, 2022). "However, the levels of TNF-α, MCP-1 and MIP-2α were not altered in stroke mice when compared to sham-surgery mice." (PMID 30842652, 2019). "Among subjects with lacunar subtype and metabolic syndrome, PWV (after correction for age and gender) was more significantly and positively related to CRP, IL-1β, IL-6, TNF-α, vWF and PAI-1 compared to subjects without metabolic syndrome and the same subtype of stroke." (PMID 24571954, 2014). "Our study clearly revealed that KO mice exhibited extremely elevation of TNF-α, IL-1β, and IL-6, suggesting that the absence of IRAK-M can exacerbate the brain tissue injury of stroke through releasing larger amounts of proinflammatory cytokines in the acute phase of stroke." (PMID 30622459, 2018).